ARPIN-AP3S2 (ARPIN-AP3S2 readthrough)
Synonyms: C15orf38-AP3S2
Gene: Protein-coding gene on chromosome 15 (89,834,308 to 89,912,882, reverse strand). Ensembl gene ENSG00000250021.
Genetic constraint (gnomAD): Loss-of-function variants: 41 observed, 45.31 expected, observed/expected ratio (o/e) 0.9, 90% interval 0.7 to 1.17. The upper end of that interval is the gene's LOEUF score, 1.17, which puts it in group 5 of 6, group 1 being the genes least tolerant of losing a copy. Missense variants: 540 observed, 523.89 expected, observed/expected ratio (o/e) 1.03, 90% interval 0.96 to 1.11. Synonymous variants: 203 observed, 207.22 expected, observed/expected ratio (o/e) 0.98, 90% interval 0.87 to 1.1.